IFITM3 (interferon induced transmembrane protein 3)
Diseases named in the same sentence as IFITM3 in open-access papers (continued):
Sharing a sentence is not in itself a finding about the gene and the disease.
viral infection (continued). "IFITM proteins, with the greatest emphasis on IFITM1, IFITM2 and IFITM3, exert inhibitory effects during viral infection." (PMID 36466909, 2022). "We found that high basal expression in monocytes of antiviral interferon-induced transmembrane protein 3 (IFITM3) limited viral infection in these cells." (PMID 35359920, 2022). "Previously, our group demonstrated that viral infections such as dengue and influenza increase systemic IFNs, which then upregulate the expression and function of IFITM3 in megakaryocytes and platelets." (PMID 36194487, 2022). "Viral infection increases IFITM3 methylation by supporting the IFITM3-SET7 interaction and thus impairs IFITM3 antiviral activity." (PMID 36466909, 2022). "IFITM3 plays a key role in the host defense against viral infections by binding to virus particles and shuttling them to lysosomes for degradation." (PMID 34724825, 2021). "This is particularly interesting since IFITM3 AH1 is important in inhibiting viral infection in cells." (PMID 34981045, 2021). "In support of this idea, it was recently shown that expression of the innate immune protein IFITM3, either constitutively or as a consequence of virus infection, directly modulates γ-secretase to produce higher amounts of Aβ." (PMID 34154615, 2021). "Recent evidence suggests a direct role for MKs in viral infections (in part via IFITM3 upregulation) and in systemic inflammation, highlighting the importance of MKs and their interactions with other immune cells." (PMID 34721400, 2021). "These significant studies in cellular and animal models as well as preliminary clinical observations highlight an important function for IFITM3 in host immunity against viral infections." (PMID 34981045, 2021). "Interferon-induced transmembrane proteins (IFITM1, IFITM2 and IFITM3), which share highly conserved palmitoylation sites, are involved in host immune response to viral infections." (PMID 33653086, 2021). "The physiological importance of IFITM3 in the control of many virus infections in vivo is becoming increasingly apparent." (PMID 33112230, 2020). "The epithelial cell and resident leukocytes in lung upper and lower airways that constitutively express IFITM3 can withstand viral infections, and this is vital to decide viral tropism as viruses favor cells with low IFITM3 expression." (PMID 32595654, 2020). "IFITM3 was found to be one of the most potent antiviral factors in restricting influenza virus infection, as IFITM3 knockout mice displayed enhanced morbidity and mortality associated with pandemic influenza H1N1/09 virus infection." (PMID 32321380, 2020). "It seems that bats (order Chiroptera), which act as natural hosts for many viral infections, use IFITM3 as an antiviral mechanism if there is S-palmitoylation of the protein; however, if this modification is disturbed, the bat can develop viral infection." (PMID 32595654, 2020). "IFITM3 and immunity are closely related and play an important role in viral infections, specifically following IFN stimulation." (PMID 33364194, 2020). "Upon virus infection, IFITM3 interacts with the incoming virus particles and directs them to lysosomes for elimination." (PMID 33195285, 2020). "Conversely, a different study described that rs34481144A had a protective effect against severe viral infection under the dominant model, as well as similar IFITM3 promoter activity when comparing rs34481144 WT and mutant HeLa cells." (PMID 32754450, 2020). "Thought to be inherently expressed to protect cells from viral infections, IFITM3 levels went down with cell differentiation." (PMID 33364194, 2020). "When duck IFITM1, IFITM2, IFITM3, and IFITM5 were overexpressed in DF-1 cells and challenged with LPAI, only IFITM3 significantly decreased viral infection." (PMID 32477965, 2020). "We find that IFITM3 is rapidly up-regulated on T cells following their activation in the draining LN and expression is maintained as these cells infiltrate sites of virus infection." (PMID 30650117, 2019).
viral infection (continued). "Up-regulation of IFITM3 on effector T cells protected these cells from virus infection and imparted a survival advantage at sites of virus infection." (PMID 30650117, 2019). "Large increases in the protein expressions of MAVS, IFN-β, and IFITM3 were observed upon viral infection." (PMID 30792656, 2019). "The findings showed that low pH treatment promoted virus infection but displayed an antagonistic effect on the restricted role of IFITM3." (PMID 29503647, 2018). "Among the number of single-nucleotide polymorphisms (SNPs) in IFITM3 gene that have been identified in human populations, several are associated with disease severity and prognosis of influenza A virus (IAV) and other viral infections." (PMID 30687247, 2018). "The primary mechanism by which IFITM3 inhibits virus infection is via blockade of fusion pore formation between virus and host membranes." (PMID 30662816, 2018). "Prior studies have revealed that the IFITM3 protein restricts virus infection at the early stage of the viral replication cycle of several RNA virus, such as IAV, WNV, and DENV." (PMID 29503647, 2018). "Viral disease in Ifitm3–/– mice was accompanied by elevated production of cytokines, most notably IL-6." (PMID 28240600, 2017). "In this review, we highlight the multiple roles played by the interferon-induced transmembrane (IFITM) proteins during viral infection, with focuses on IFITM3 and HIV-1." (PMID 29162141, 2017). "The result was dysregulation of cellular immunity and impaired control of virus replication, suggesting that murine IFITM3 plays a part in regulating cytokine production important for resolution of virus infection." (PMID 29162141, 2017). "In this regard, IFITM3 protein encoded by IFITM gene, have shown to be associated with susceptibility to several viral infections, such as West Nile virus, dengue virus, rhinovirus, corona virus, HIV, respiratory syncytial virus, and influenza A virus." (PMID 29121968, 2017). "We now provide what we believe to be direct evidence of a link between excessive cytokine production as a consequence of impaired IFITM3 function and fatal viral infection." (PMID 28240600, 2017). "It has been known post-translational modifications of IFITM3 would regulate its action against virus infection." (PMID 29281729, 2017). "We now show that induction of IFITM3 expression alone by type I IFN protects this DC type from viral infection, allowing its migration from the lung mucosa to the LN to exert its anti-viral function." (PMID 26600246, 2015). "The role of IFITM3 in restricting virus infections, where the virus enters the cell through the acidic endosomal pathway, is well established." (PMID 24278312, 2013). "Selected antiviral genes (IFI6, IFIT3 and IFITM3) were also up-regulated, indicating that PAMs were attempting to control the viral infection." (PMID 23527143, 2013). "Previous studies revealed that IFITM2 and IFITM3 (two structurally related cell plasma membrane proteins) interrupt early steps entry and/or uncoating of the viral infection." (PMID 22397681, 2012). "Expression of human IFITM3 in canine and chicken cells also prevented viral infection, suggesting that IFITM proteins utilize an evolutionarily conserved pathway to elicit an antiviral state." (PMID 21994648, 2010). "IFITM3 was identified as an antiviral protein by showing that its knockdown significantly enhances viral infection." (PMID 21994648, 2010). "However, further studies using stable IFITM3 knockout systems are required to address how long IFITM3 downregulation can be maintained in infected megakaryocytes to sustain viral infection in these cells." (PMID 39354676, 2025). "Collectively, these findings reinforce the critical role of IFITM3 in emergent viral infections and further suggest that the compensatory role of adaptive immunity may explain the inconsistent associations observed in studies of seasonal influenza." (PMID 40237465, 2025).
viral infection (continued). "IFITM3 plays an important role in autophagy during some viral infections." (PMID 40681213, 2025). "In agreement with GO analysis, the expression of immune‐related genes such as Ccl genes, Cxcl genes, Il6, Tnf, and Ifitm3 were further increased in the lungs of opt‐hACE2 mice after viral infection, highlighting a more pronounced immune response in these mice compared to the other mouse models." (PMID 39737574, 2025). "IFITM3 has been reported to interact with HBV receptor NTCP to facilitate virus infection." (PMID 40434075, 2025). "IFITM3 is an IFN-stimulated gene that regulates viral infection through autophagy; however, its role in C. parvum infection is unknown." (PMID 40681213, 2025). "Here, we investigate whether Interferon-Induced Transmembrane Protein 3 (IFITM3), a host antiviral factor with known human deficiencies, plays a role in interspecies virus infection and adaptation." (PMID 39477971, 2024). "Ifitm3 restricts various viral infections and is closely related to the antiviral ability of cells." (PMID 39196711, 2024). "IFITM3 exhibits a broad-spectrum inhibitory activity against a variety of viral infections." (PMID 39459876, 2024). "IFITM3 is induced by viral infection and cytokines, it is likely that it acts downstream of cytokine activation, which may partly explain why its overexpression does not impact inflammatory activation and signaling mediators TLR4 and NF-κB." (PMID 37602193, 2023). "In addition, we noted expression of genes mediating anti-viral response (i.e., CH25H and IFITM3), which confers high viral infection resistance to various tissue SCs." (PMID 37652013, 2023). "Additionally, the AUC–ROC values for IFITM3 rs34481144 were 0.540, showing that host genetic factors commonly influence viral infection mortality." (PMID 37323564, 2023). "They modified IFITM3 Cys72 with maleimide-palmitate and showed that lipid modification at Cys72 stabilizes IFITM3 amphipathic helix membrane interaction, which is important for the restriction of virus infections." (PMID 38140570, 2023). "Mechanistically, IFITM3 regulates viral infections in part through modulating endocytosis." (PMID 36194487, 2022). "However, the presence of IFITM3 conferred cellular protection against viral infection, leading to its selectively maintained expression, as was described in lung tissue-resident memory T cells." (PMID 36466909, 2022). "Interestingly, Dorf and colleagues reported that MEFs knocked out for Ifitm1-3 that overexpressed human ZMPSTE24 were resistant to infection by multiple viruses, but MEFs knocked out for Zmpste24 that overexpressed IFITM3 were sensitive to viral infection." (PMID 36197088, 2022). "Among the upregulated ISGs, 27 ISGs, including IRF1, IRF7, IFITM1, and IFITM3, play antiviral roles in different stages of virus proliferation, thus inhibiting or delaying the process of virus infection by interacting with other proteins or ISGs to form a complex protein–protein interaction network." (PMID 35401515, 2022). "Downregulation of IFITM3 by meth could result in increased viral infection of mature monocytes due to impaired ability to reduce viral entry and/or degradation of the virus." (PMID 36059515, 2022). "As the results showed, IFITM3 may limit virus infection in both the early endocytosis and endosomal penetration phases, since virus receptor binding was not affected." (PMID 36366505, 2022). "Broilers show more resistance to viral infection than layers, a notable feature of the IFITM3 gene." (PMID 34828268, 2021). "The high expression of several interferon-induced viral-response genes (e.g. Bst2, Ifitm3, Ube2l6, and Rnf213) in the control ‘interferon’ cluster might point to a state of general surveillance for viral infection at baseline." (PMID 34939923, 2021).
viral infection (continued). "The study showed that IFITM3 clustering increased following influenza virus uptake, with IFITM3 coating early and recycling endosomes that contained viral NP (i.e., pre-fusion), potentially preventing virus infection at an early timepoint." (PMID 33540739, 2021). "Besides, the protective effect of IFITM3 is also reflected in the long survival of lung resident memory T cells, in which sustained IFITM3 expression facilitated their survival and protection from viral infection during subsequent exposure." (PMID 34818332, 2021). "Recent NMR studies with IFITM3 chemically modified at Cys72 with maleimide-palmitate show that lipid modification at Cys72 stabilizes IFITM3 amphipathic helix membrane interaction which is important for restriction of virus infection." (PMID 33653086, 2021). "Indeed, module 3 included three IFN-induced transmembrane (IFITM) genes (IFITM1, IFITM2, IFITM3), involved in the restriction of multiple viruses, that were overexpressed in patients with viral infection and positively correlated with severity." (PMID 33765435, 2021). "In the lung tissue-resident memory CD8+ T-cells, IFITM3 expression could be up-regulated by antigen recognition or interferon-α to protect from viral infection." (PMID 33061814, 2020). "Besides this, IFITM1-3, especially IFITM3, is also expressed in T cells and lymphocytes, which can protect immune cells and the lungs, airway, spleen, skin, and brain from viral infection by stimulating effective immune responses." (PMID 33329509, 2020). "Remarkably, IFITM3 can inhibit H7N9 replication early in viral infection." (PMID 30944006, 2019). "Moreover, lung resident memory CD8+ T cells in mice were programmed to retain IFITM3 expression, facilitating their survival and protection from viral infection during subsequent exposures." (PMID 30687247, 2018). "Thus, at present, the critical role of IFITM3 in antimicrobial defense appears to be limited to virus infections, though this remains an open question." (PMID 30662816, 2018). "Fifth, IFITM3 gene SNPs in the human population are correlated with severe virus infections." (PMID 30662816, 2018). "Importantly, genetic studies emphasize the pivotal role that IFITM3 plays in governing viral disease in humans." (PMID 28240600, 2017). "However, little is known about the responsible host enzymes catalyzing these post-translational modifications on IFITM3 and how important these modifications are in host protection against virus infection." (PMID 29281729, 2017). "A balance between the lysine methylation and demethylation of IFITM3 at K88 may exist to maintain the cell homeostasis, and this balance may be broken under virus infection." (PMID 29281729, 2017). "Therefore, IFNα signals strengthen host restriction factors through demethylating K88me1 on IFITM3 by LSD1, and virus infection counteract host restriction factors by promoting methylation of IFITM3 at K88." (PMID 29281729, 2017). "Genes in this signature code for proteins that are viral infection restricting factors (e.g. Ifitm1, Ifitm3, Gbp7), that protect against cellular or environmental stress (e.g. Abcb1a, Car2, Ern1, Serpina3g) or that regulate immune activation processes (e.g. Fgl2, Anxa1, Havcr2)." (PMID 27883012, 2016). "We cannot exclude the possibility that IFITM3 may be able to adopt multiple topologies in different stages of the viral infection period, or in different host cell types." (PMID 27046158, 2016). "The functional homology of the bacterial IFITMs with IFITM3 could indicate that transfer of a bacterial IFITM to eukaryotes offered an advantage against virus infection that was refined through co-evolution with viruses." (PMID 26075508, 2015). "Thus, identification of the IFITM3 ubiquitin ligase would provide a potential target for increasing IFITM3 abundance and resistance to virus infections." (PMID 26263374, 2015).
viral infection (continued). "Therefore, we have identified NEDD4 as a regulator of IFITM3 levels and as a novel drug target for preventing influenza virus and other IFITM3-sensitive virus infections." (PMID 26263374, 2015). "Convergently evolved amino acids between primates and rodents were found in the C-terminus of IFITM2 and IFITM3 (data not shown), a crucial region for antiviral activity, supporting the association between viral infections and the evolution of IR-IFITM genes." (PMID 23166625, 2012). "Therefore, our description of an R-SNARE-like motif in IFITM3 may reveal the molecular basis by which IFITM3 interacts with both cellular and viral fusion machinery to control virus infections at multiple levels." (PMID 39653855, 2025). "While the high prevalence of IFITM3 SNPs in these groups is puzzling, given their association with increased viral disease severity, a negative role for IFITM3 in placental development may explain their selection and maintenance in these populations." (PMID 39477971, 2024). "Importantly, in the murine cytomegalovirus (MCMV) model of infection, Ifitm3 restricts infection-induced IL-6 mediated viral disease, lymphopenia and loss of NK and T cells without directly impacting CMV replication." (PMID 36075894, 2022). "It is also interesting to speculate as to whether during severe viral infections, the upregulation of IFITM3 in platelets and megakaryocytes may serve dual roles (e.g., immune and hemostatic functions) as other proteins, such as fibrinogen, in platelets are known to do." (PMID 36194487, 2022). "Therefore, it is important to understand how IFITM3 counters virus infection." (PMID 31398796, 2019). "There is significant evidence for a protective role of IFITM3 against virus infections in both mice and humans, though additional work is required to identify the range of pathogens restricted by IFITM3 and the mechanisms by which human SNPs affect IFITM3 levels or functionality." (PMID 30662816, 2018). "Interestingly, the silencing of endogenous IFITM3 protein enhanced the cell death caused by VTT infection, suggesting that IFITM3 may have a role in mediating resistance to virus infection." (PMID 29503647, 2018). "For example, components of the innate immunity have proved to significantly contribute to the effective control of viral infections, such as interferon-induced cellular restriction factors (e.g. Interferon-induced transmembrane protein 3; IFITM3) that may target both HIV-1 and influenza A." (PMID 24978204, 2014). "The highest ratio in this set was two-fold and out of the top 10 specificities, 7 were in the Type I interferon signature (IFITM3, MX1, IFI6, IFI44L, ISG15, OAS1, IFIT3) and one encodes a protein that is activated by dsRNA as might be present in a viral infection (EIF2AK2)." (PMID 21366908, 2011). "Here, we show that two human IFITM proteins known for performing antiviral roles during virus infection, IFITM1 and IFITM3, interact with one another in endolysosomes." (PMID 42262132, 2026). "A study has demonstrated that the expression of the transmembrane protein Interferon-induced transmembrane protein 3(IFITM3), which facilitates survival and resistance to viral infection during subsequent exposures in CD8+TRM, is regulated by DNA methylation." (PMID 40895552, 2025). "The observed elevation of ISGs, encompassing ISG15, IFI6, IFIT1, IFIT2, IFIT3, IFI44L, and IFITM3, highlights SARS-CoV-2’s ability to activate the host’s interferon response—a critical defence mechanism against viral infection." (PMID 39940816, 2025). "For example, interferon‐induced transmembrane protein 3 (IFITM3) is a member of the IFITM family, which is composed of important innate immune effectors involved in protecting against diverse viral infections in vertebrates." (PMID 39964025, 2025). "VirSig was defined as the signature of the host response to viral infection using the average expression of five representative genes, including IFI27, RSAD2, IFI44L, ISG15 and IFITM3." (PMID 38790931, 2024).